CYP46A1 (cytochrome P450 family 46 subfamily A member 1)
Diseases named in the same sentence as CYP46A1 in open-access papers (continued):
Sharing a sentence is not in itself a finding about the gene and the disease.
Parkinson disease (7 papers, 2019 to 2025). A progressive degenerative disorder of the central nervous system characterized by loss of dopamine producing neurons in the substantia nigra and the presence of Lewy bodies in the substantia nigra and locus coeruleus. "The cholesterol 24-hydroxylase (CYP46A1) has been linked to neurodegenerative disease, but it’s direct contribution to Parkinson’s disease is unknown." (PMID 39964974, 2025). "Single nucleotide polymorphisms (SNPs) with statistically significant association (p-value <0.05) to Parkinson ́s Disease (PD) for the genes of the four human cholesterol degrading cytochrome P450, CYP7B1, CYP27A1, CYP39A1 and CYP46A1." (PMID 39403150, 2024). "Taken together, these expression data indicate that mainly CYP46A1 might play an important role in dopaminergic neurons and the context of Parkinson’s disease." (PMID 39403150, 2024). "Much less is known about the role of CYP46A1 in Parkinson's disease." (PMID 30655290, 2019). "For instance, it remains to be determined whether the level and functionality of CYP46A1 are conserved or altered in Parkinson's disease models or patients." (PMID 30655290, 2019).
glaucoma (6 papers, 2011 to 2023). Increased pressure in the eyeball due to obstruction of the outflow of aqueous humor. "While the data detailed above suggest a role of oxysterols, especially CYP46A1 product, in glaucoma, the characterization of the retina of mice deficient in CYP enzymes does not absolutely confirm this idea." (PMID 38983043, 2023). "We reported for the first time an association between a Cyp46a1 gene variant (rs754203) and increased risk of glaucoma in a French population." (PMID 38983043, 2023). "The data obtained demonstrate an important APOJ role in retinal cholesterol homeostasis and link this apolipoprotein to the glaucoma risk factors and retinal 24-hydroxycholesterol production by CYP46A1." (PMID 37392222, 2023). "(section 3.2), experimental models of glaucoma are associated with early increases in retinal CYP46A1 expression and 24S-OHC levels." (PMID 38983043, 2023). "Genotype distribution and allele frequency of the CYP46A1 IVS2 –150 C>T polymorphism (rs754203) in patients with primary open angle glaucoma (POAG)." (PMID 21386929, 2011). "Interestingly, the same gene variant of Cyp46a1 has been linked to an increased risk of AD, which shares some features with glaucoma." (PMID 38983043, 2023). "These evaluations, along with EFV treatment and characterization of Cyp46a1−/− mice, revealed the novel APOJ-24HC/CYP46A1 link and suggested a principally new therapeutic approach for reducing glaucoma risk factors based on CYP46A1 activation with low-dose anti-HIV drug EFV." (PMID 37392222, 2023). "Finally, a single nucleotide polymorphism in the gene coding for CYP46A1 was found to be associated with a higher risk for developing glaucoma, a neurodegenerative disease of the retina and the optic nerve." (PMID 35275950, 2022). "Genotype distribution and allele frequency of the CYP46A1 IVS2 –150 C>T polymorphism (rs754203) in patients with primary open angle glaucoma (POAG) with early (mean defect [MD] above −6 dB), moderate (MD between −6 and −12 dB) and severe (MD below −12dB) defect." (PMID 21386929, 2011). "To obtain support that the observed improvements in the glaucoma risk factors in EFV-treated Apoj−/− mice were mediated by CYP46A1 activation, we evaluated Cyp46a1−/− mice." (PMID 37392222, 2023). "The specific expression of CYP46A1 in RGCs, the cellular target of glaucoma, points toward a possible role of the enzyme and its product 24S-OHC in this disease." (PMID 38983043, 2023). "The localization of CYP46A1 in RGC supports a possible role of 24(S)-HC in glaucoma because RGC are the cells most affected by elevated retinal pressure." (PMID 27653972, 2016). "An intronic single nucleotide polymorphism in the gene CYP46A1 (IVS2 −150 T>C; rs754203) has recently been associated with primary open angle glaucoma (POAG)." (PMID 21386929, 2011). "A polymorphism (rs754203) in CYP46A1 was proposed to be a risk factor for primary open-angle glaucoma (POAG), but a subsequent study did not replicate this association." (PMID 37392222, 2023). "Altogether, the data detailed above indicate that CYP46A1 expression could be beneficial in the context of glaucoma." (PMID 38983043, 2023). "In the present study using an ex vivo glaucoma model, we examined whether retinal 24(S)-HC synthesis is altered by activation of CYP46A1." (PMID 27653972, 2016). "Since glaucoma presents common features with neurodegenerative diseases of the CNS, it is interesting to consider that apoptotic neuronal death was also observed in the hippocampus of mice with CYP46A1 inhibition induced by a ShRNA-coding AAV targeting neurons." (PMID 38983043, 2023). "Thus, the relationship between cyp46a1 and glaucoma remains uncertain." (PMID 27653972, 2016). "Interestingly, elevated IOP has been shown to induce an increase in the levels of CYP46A1 and its product 24S-OHC, in an ex-vivo model of glaucoma." (PMID 35275950, 2022).
glaucoma (continued). "Animal models of glaucoma showed that elevated IOP induces either a transient increase in retinal CYP46A1 but not 24HC levels (laser photocoagulated eyes) or a pressure-dependent increase in both retinal CYP46A1 expression and 24HC levels (ex vivo retina under high pressure)." (PMID 37392222, 2023). "However, the consequences of this genetic variation on CYP46A1 enzyme protein levels and activity is unknown since plasma 24S-OHC levels were not different between the different genotypes or between glaucoma patients and controls." (PMID 38983043, 2023).
glioblastoma (6 papers, 2020 to 2024). The most malignant astrocytic tumor (WHO grade IV). "Loss of CYP46A1 partially caused excessive cholesterol accumulation in glioblastoma cells contributing to the maintenance of tumour cell viability and a malignant state." (PMID 31777202, 2020). "In glioblastoma, the expression of CYP46A1 is significantly reduced and correlates with tumor grade and prognosis." (PMID 38725627, 2024). "More recently, investigations of PD, ALS, and MS as well brain trauma, neonatal hypoxia, and glioblastoma have reinforced the interest for 24HC as a biomarker of disease progression and highlighted the role of CYP46A1 in this process or even disease genesis." (PMID 34305573, 2021). "Here, we analysed cholesterol homeostasis‐related genes systematically in glioblastoma databases and identified a functional role of cholesterol 24‐hydroxylase (CYP46A1) in glioblastoma growth and progression." (PMID 31777202, 2020). "Altered cytoskeletal phosphorylation in mice with altered sterol flux could explain in part why brain diseases such as neurodegenerative disorders, seizures, depression, and even cancer (glioblastoma) could benefit from CYP46A1 activity modulation." (PMID 34235635, 2021). "In mouse models, modulations of CYP46A1 activity mitigate the manifestations of Alzheimer’s, Huntington’s, Nieman-Pick type C, and Machao-Joseph (spinocerebellar ataxia type 3) diseases as well as amyotrophic lateral sclerosis, epilepsy, glioblastoma, and prion infection." (PMID 34305573, 2021).
memory impairment (5 papers, 2018 to 2025). "Disruption of CYP46A1 function leads to an accumulation of cholesterol esters within neurons, a phenomenon linked to memory impairments and adverse effects in AD." (PMID 40126262, 2025). "Indeed, based on experiments with mouse models the possibility has been discussed that there may be a causal link between CYP46A1 protein content and memory impairment that result from Tau pathology." (PMID 30245667, 2018). "These sex-specific effects, including protection from memory impairments induced by ovariectomy in females, highlight the translational relevance of CYP46A1 regulation in human AD." (PMID 40126262, 2025). "And then injection of adeno-associated vector (AAV) encoding CYP46A1 into the hippocampus of THY-Tau22 mice led to CYP46A1 content normalization and completely rescued memory impairment." (PMID 33967789, 2021). "In aged female mice, CYP46A1 overexpression enhances estrogen signaling within the hippocampus, leading to improved cognitive functions, whereas in males, it results in anxiety-like behavior, memory impairment, and elevated 5α-dihydrotestosterone levels." (PMID 40126262, 2025). "Inhibition of CYP46A1 activity in the APP23 AD mouse model limits cholesterol export from the brain and increases levels of hyperphosphorylated Tau (pTau), while overexpression of CYP46A1 (to induce export of brain cholesterol) in THY-Tau22 mice rescues Tau-mediated memory impairment." (PMID 41318029, 2025).
glioma (4 papers, 2019 to 2021). A benign or malignant brain and spinal cord tumor that arises from glial cells (astrocytes, oligodendrocytes, ependymal cells). "Loss of CYP46A1 in GBM was further confirmed by analysing several public glioma datasets (over 1,500 samples were enrolled; P < 0.01, respectively)." (PMID 31777202, 2020). "Low expression of CYP46A1 was associated with increasing tumor grade and poor prognosis in human gliomas." (PMID 32802843, 2020). "A reduction in CYP46A1 expression was associated with increasing tumour grade and poor prognosis in human gliomas." (PMID 31777202, 2020). "Moreover, through large‐scale survival analysis, we showed that low CYP46A1 expression in glioma tissues is associated with poor prognosis and can therefore serve as an independent prognostic indicator." (PMID 31777202, 2020). "We also examined the active enhancer landscape of CYP46A1 across three matched pairs of GSCs and differentiated glioma cells (DGCs)." (PMID 31777202, 2020). "We subsequently assessed CYP46A1 levels based on the 2016 WHO classification of gliomas, using the TCGA data." (PMID 31777202, 2020). "Mechanistically, ectopic expression of CYP46A1 suppressed glioma stem cell proliferation and in vivo tumour growth by increasing 24OHC, which led to a decrease in GBM cholesterol levels." (PMID 31777202, 2020). "To confirm that CYP46A1 expression is reduced in GBMs at the protein level, we performed IHC staining for CYP46A1 on an independent cohort of glioma (n = 58) and normal brain tissue samples (n = 6)." (PMID 31777202, 2020). "Differential analysis based on the Chinese Glioma Genome Atlas (CGGA) dataset also revealed CYP46A1 as one of the most dysregulated transcripts (log2 fold change = 1.966, adjusted P = 4.63E‐09) between GBM (n = 128) and normal brain (n = 5; Fig EV1A–C)." (PMID 31777202, 2020). "The expression of CYP46A1 was negatively correlated with WHO grade and malignant clinicopathological features of gliomas." (PMID 31777202, 2020). "Furthermore, increased expression of CYP46A1 in GSCs (GBM#P3) inhibited tumorsphere formation, a critical glioma stem‐like property (P < 0.05)." (PMID 31777202, 2020). "Additionally, analysis based on 1,018 Chinese glioma patients suggested that CELF5 (P < 0.001), GSG1L (P = 0.002), AMACR (P < 0.001), CYP27A1 (P < 0.001), CYP46A1 (P < 0.001), and CH25H (P = 0.046) were all prognostic indicators in Kaplan-Meier survival analysis." (PMID 32117422, 2019).
neuroblastoma (4 papers, 2013 to 2025). Neuroblastoma (NB) is the most common solid, extracranial childhood tumor. "Similar to EFV treatment, CYP46A1 overexpression in mouse-adapted scrapie prion–infected mouse neuroblastoma N2a cells reduced PrPSc, demonstrating a causal correlation between enhanced CYP46A1 activity and reduced PrPSc levels." (PMID 40540390, 2025). "Following our previous studies in HD, in this study we aim to investigate in vitro in a neuroblastoma cellular model of HD, the effect of CYP46A1 overexpression, an essential enzyme in cholesterol metabolism, on huntingtin aggregation and levels." (PMID 32276655, 2020). "We analyzed by immunocytochemistry the impact of CYP46A1 overexpression in neuroblastoma (N2a) cells overexpressing the exon 1 of HTT-MUT carrying 74 glutamine (Q74) fused with GFP." (PMID 32276655, 2020). "Here, we further show that CYP46A1 is able to decrease the number and size of HTT-MUT aggregates within a neuroblastoma cellular model of HD." (PMID 32276655, 2020).
Niemann-Pick disease type C (3 papers, 2019 to 2026). NPC is a complex lipid storage disease mainly characterized by the accumulation of unesterified cholesterol in the late endosomal/lysosomal compartment. "CYP46A1 can be allosterically activated with low-dose anti-HIV drug efavirenz and mitigate the manifestations of various neurologic diseases in mouse models and Niemann-Pick type C disease in humans." (PMID 42066672, 2026).
prion disease (3 papers, 2021 to 2025). A transmissible disease that is caused by a protein that is able to induce abnormal folding of normal cellular proteins, leading to characteristic spongiform brain changes, which are associated with neuronal loss without an inflammatory response. "Our results demonstrate that EFV has significant beneficial effects in prion disease, likely associated with Cyp46A1 activation, eventually regulating impaired brain cholesterol metabolism." (PMID 33795005, 2021). "In line with this, we demonstrate here that Cyp46A1 activation represents a novel and efficient therapeutic strategy against prion diseases." (PMID 33795005, 2021). "Cyp46A1 signals were quantified, and the results indicate a significant reduction of Cyp46A1 in brain homogenates at the terminal stage of prion disease (RML, 22L, and ME7; p < 0.01) compared to the age-matched non-infected mice (p < 0.01)." (PMID 33795005, 2021). "Our finding of Cyp46A1 downregulation is one among other examples showing a specific protein that is affected in prion disease." (PMID 33795005, 2021). "Overall, our results suggest that increasing Cyp46A1 activity in prion diseases can be a novel therapeutic approach in prion diseases." (PMID 33795005, 2021). "Our results, together with evidence from other studies indicate a role of Cyp46A1 in aberrant brain cholesterol metabolism in neurodegenerative diseases and that it would be a valuable and novel drug target in prion diseases." (PMID 33795005, 2021). "Of note, as in the experimental models of prion disease, a significant reduction of Cyp46A1 levels in the brains of sCJD patients as compared to the healthy individuals was observed, confirming the relevance of our finding to human prion diseases (p < 0.05)." (PMID 33795005, 2021). "The reduction of Cyp46A1 we observed both in vivo and in vitro indicates that Cyp46A1 has a role in prion diseases." (PMID 33795005, 2021). "In summary, our results demonstrate that regulation of brain cholesterol metabolism through pharmacological activation of Cyp46A1 using EFV is a promising approach for intervention in prion diseases." (PMID 33795005, 2021). "To assess a potential role of Cyp46A1 in prion disease, we analyzed its protein levels at the terminal stage of prion disease after intracerebral (i.c.)inoculation of three well established scrapie strains (RML, 22L and ME7) into FVB mice." (PMID 33795005, 2021). "In summary, we show for the first time a reduction of Cyp46A1 levels in prion disease, and its value as an accessible therapeutic target." (PMID 33795005, 2021). "Importantly, EFV could effectively cross BBB with a significant reduction in Cytochrome P450 Family 46 Subfamily A Member 1 (CYP46A1) levels in prion disease." (PMID 36515657, 2022). "For the first time, we demonstrate that Cyp46A1 protein level is reduced at terminal stages of prion disease in mice independent of the prion strain used for infection, and more importantly, in post-mortem brains of sCJD patients." (PMID 33795005, 2021). "In summary, our results suggest that Cyp46A1 as a novel therapeutic target and that its activation through repurposing the anti-retroviral medication EFV might be valuable treatment approach for prion diseases." (PMID 33795005, 2021). "However, the role of Cyp46A1 in prion diseases has not yet been studied." (PMID 33795005, 2021). "However, drugs effective against scrapie prions often fail in human prion diseases, and a relation of the antiprion effects of EFV to CYP46A1 activation is not established." (PMID 40540390, 2025).
Anxiety (2 papers, 2024 to 2025). Intense feelings of nervousness, tension, or panic often arise in response to interpersonal stresses. "Conversely, age-matched male mice with CYP46A1 overexpression exhibit anxiety-like behavior, impaired memory, and increased levels of 5α-dihydrotestosterone in the hippocampus." (PMID 39964974, 2025). "In contrast, age-matched CYP46A1 overexpressing males show anxiety-like behavior, worsened memory, and elevated levels of 5α-dihydrotestosterone in the hippocampus." (PMID 38266095, 2024). "We performed a battery of behavioral tests to evaluate anxiety-like behavior and hippocampal-dependent learning and memory in 18-month-old CYP46A1 overexpressing male and female mice (Cyp46Tg) and their age-matched wild-type littermates (Tg−)." (PMID 38266095, 2024).
colorectal cancer (2 papers, 2016 to 2024). A primary or metastatic malignant neoplasm that affects the colon or rectum. "CYP46A1 has been identified as a promoter of colorectal cancer progression by inducing tumor cell proliferation and angiogenesis." (PMID 38725627, 2024). "The findings of increased expression of CYP8B1 and CYP46A1 in primary colorectal cancer are novel findings." (PMID 27341022, 2016). "The intensity of immunostaining was significantly higher in primary colorectal cancer compared with normal colonic mucosa for CYP2R1 (p<0.001), CYP7B1 (p<0.001), CYP8B1 (p<0.001), CYP46A1 (p<0.001) and CYP51A1 (p=0.001)." (PMID 27341022, 2016). "Immunohistochemistry was performed on a colorectal cancer tissue microarray containing 650 primary colorectal cancers using monoclonal antibodies to CYP2R1, CYP7B1, CYP8B1, CYP27A1, CYP39A1, CYP46A1 and CYP51A1, which we have developed." (PMID 27341022, 2016). "This study has profiled the expression of the cholesterol metabolising enzymes CYP2R1, CYP7B1, CYP8B1, CYP27A1, CYP39A1, CYP46A1 and CYP51A1 in primary colorectal cancer tissue using a well-characterised cohorts of colorectal cancers." (PMID 27341022, 2016). "However, CYP2R1 (p=0.034), CYP8B1 (p=0.002), CYP39A1 (p<0.001), CYP46A1 (p<0.001) and CYP51A1 (p=0.001) each demonstrated significantly reduced expression in paired lymph node metastasis compared to Dukes C (stage 3) colorectal cancer." (PMID 27341022, 2016). "CYP2R1, CYP7B1, CYP8B1, CYP46A1 and CYP51A1 all showed significantly increased expression in primary colorectal cancer compared to normal colonic mucosa with CY7B1 demonstrating the highest proportion of strong immunoreactivity in colorectal cancer compared to all other enzymes studied." (PMID 27341022, 2016).
diabetic retinopathy (2 papers, 2019 to 2023). "A second CYP enzyme of interest is CYP46A1, which converts cholesterol to 24-hydroxycholesterol, as retinas from Cyp46a1−/− mice exhibit venous beading and tortuosity, microglia/macrophage activation, and increased vascular permeability, features commonly associated with diabetic retinopathy." (PMID 31333461, 2019). "Third, CYP46A1 may play a role in glaucoma and diabetic retinopathy." (PMID 36914277, 2023). "In addition, CYP46A1 could play a protective role in vascular damage in diabetic retinopathy." (PMID 36914277, 2023).